NRN1L (neuritin 1 like)
Synonyms: UNQ2446; MRCC2446; cpg15-2
Tractability: Antibody: UniProt places it where antibodies can reach, with high confidence; its Gene Ontology location is reachable by antibodies, with high confidence; UniProt predicts a signal peptide or a membrane-spanning region.
Gene: Protein-coding gene on chromosome 16 (67,884,885 to 67,888,855, forward strand). Ensembl gene ENSG00000188038.
Subcellular location: Cell membrane
Pathways (Reactome):
Metabolism of proteins: Post-translational modification: synthesis of GPI-anchored proteins
Gene Ontology:
Molecular function: protein binding; identical protein binding
Biological process: neuron projection extension; nervous system development
Cellular component: extracellular region; plasma membrane; axon; membrane
Genetic constraint (gnomAD): Loss-of-function variants: 11 observed, 8 expected, observed/expected ratio (o/e) 1.38, 90% interval 0.85 to 1.9. That is too few expected variants to judge how well the gene tolerates losing a copy. Missense variants: 260 observed, 218.59 expected, observed/expected ratio (o/e) 1.19, 90% interval 1.07 to 1.32. Synonymous variants: 113 observed, 92.18 expected, observed/expected ratio (o/e) 1.23, 90% interval 1.05 to 1.43.
Homologues: Orthologues: chimpanzee NRN1L (98% identical), macaque NRN1L (88% identical), rabbit NRN1L (81% identical), pig NRN1L (78% identical), mouse Nrn1l (77% identical), guinea pig NRN1L (76% identical), dog NRN1L (70% identical), zebrafish nrn1la (36% identical), tropical clawed frog nrn1l (35% identical), zebrafish nrn1lb (31% identical). Paralogues in human: NRN1 (27% identical).
Diseases named in the same sentence as NRN1L in open-access papers:
NRN1L is named in the same sentence as 4 diseases in open-access papers, as found by Europe PMC text mining. Sharing a sentence is not in itself a finding about the gene and the disease.
NRN1L shares sentences with these, for which no sentence is quoted: breast carcinoma (1 paper); neurological diseases (1); Obesity (1); psychiatric diseases (1).